IFNG (interferon gamma)
Diseases named in the same sentence as IFNG in open-access papers (continued):
Sharing a sentence is not in itself a finding about the gene and the disease.
heart failure (32 papers, 2007 to 2026). Inability of the heart to pump blood at an adequate rate to meet tissue metabolic requirements. "Several pro-inflammatory cytokines, including tumor necrosis factor-alpha (TNF-alpha), interferon-gamma, interleukin-1-beta, interleukin-6, interleukin-17, and interleukin-18 have been implicated in the pathogenesis of heart failure." (PMID 33391898, 2021). "rs6843082 (chr4:111718067:G > A) is also in an IFNγ-upregulated peak and is significant in GWAS for atrial fibrillation and flutter, cardiac dysrhythmias, and heart failure." (PMID 40104808, 2025). "Its function can be regulated by cytokines, such as IFNγ and TNFα, and it has been proposed, together with CXCL9 and CXCL11, as a biomarker for heart failure and left ventricular dysfunction." (PMID 36364913, 2022). "Investigators found significantly higher stem cell growth factor beta (SCGF beta), hepatocyte growth factor (HGF), monokine induced by interferon gamma (CXCL9), and macrophage inhibitory factor (MIF) in Chagas myocardiopathy patients with advanced heart failure compared to the control group." (PMID 38133693, 2023). "Similarly, it was shown that Th1 cells induced TGF-β production in cardiac fibroblasts and selectively drove cardiac fibrosis in an IFNγ-dependent manner, suggesting a pro-fibrotic role of Th1 cells and IFN-γ in nonischemic heart failure." (PMID 32708044, 2020).
malnutrition (32 papers, 2009 to 2025). Inadequate nutrition resulting from poor diet, malabsorption, or abnormal nutrient distribution. "Here, we found that malnutrition increases VL susceptibility due to an elevation in IL-10 production, which limits IFNγ-mediated immunity, iNOS production, and hepatic granuloma formation." (PMID 39527629, 2024). "Similarly, malnutrition affects a range of immune responses from macrophage phagocytosis and activation to T cell response and IFNγ production that results in increased TB risk." (PMID 31311495, 2019). "Our results indicate that malnutrition increases VL susceptibility due to defective activation and expansion of CD4+ IFNγ+ T cells, decreased iNOS expression, and reduced hepatic granuloma formation, which is attributable to increased IL-10 production." (PMID 39527629, 2024). "Other in vivo studies show that protein-energy malnutrition alone ↑ serum IL-10 and ↓ IFNγ suggesting that infection further alters the immune response during malnutrition." (PMID 22937528, 2012). "In mice, tissue IFNγ increased in response to malnutrition and infection with Cryptosporidium or Heligmosomoides." (PMID 22937528, 2012). "In animal models, malnutrition has been linked to reduced lymphocyte counts, as well as decreased expression of tumor necrosis factor (TNF), interferon-gamma (IFNγ), and nitric oxide synthase (NOS)-2 which are essential for generation of mycobactericidal nitrogen oxide." (PMID 30917170, 2019). "While we see epithelial cell ablation, and dextran leakage from the gut with moderate malnutrition, we do not think there is bacterial translocation in this model, based on lower systemic IFNγ and TNFα observed in the sera." (PMID 33799736, 2021). "In keeping with our results in stimulated NK cells in European adults, serum IFNγ levels in Malawian children with acute NTS bacteraemia are dependent on rs13390936 genotype (linear regression, P = 0.016), independent of age, sex, malnutrition, HIV status and malaria co-infection." (PMID 29523850, 2018).
SARS-CoV infection (32 papers, 2006 to 2025). "There is other mechanism of infection related to SARS-CoV infection which is associated with high levels of cytokines, including interleukin (IL)-1β, IL-6, IL-12, interferon gamma (INFγ) and tumor necrosis factor-alpha (TNFα)." (PMID 33613024, 2021). "IL-10, a cytokine associated with Th-2 adaptive immune response that represses IFNγ secretion, was associated with poor outcome in the early stage of SARS-CoV infection." (PMID 24551142, 2014). "In view of the large amounts of cytokines produced during SARS-CoV infection, infection with SARS-CoV-2 similarly induces the production of proinflammatory cytokines such as, interleukin 1 beta (IL-1β), interferon gamma (IFN-γ), IP10 and monocyte chemoattractant protein 1 (MCP)." (PMID 32524843, 2020).
acute GVHD (31 papers, 2004 to 2025). "The STAT6-driven Th2 pathway and immune regulatory cytokines (IL10, TGFβ) are associated with the regulation of Th1 cytokine IFNγ production and the mitigation of acute GVHD, the severity of which is more dominantly driven by Th1 cytokines." (PMID 39796136, 2024). "Furthermore, PLX2853 significantly reduced IL-23R+ and pathogenic CD4+ IFNγ+ IL-17+ double positive T cell infiltration in gastrointestinal tissues in an acute GVHD murine model." (PMID 34722316, 2021). "By day +100 (the timeframe for classical acute GVHD), the percentage of Tregs and concentration of IFNγ was comparable to healthy donors, suggesting a normalization of the bone marrow microenvironment by day +100." (PMID 34630390, 2021). "The recipient mice develop acute GVHD within the first week after transplantation, and the maximum serum levels of IFNγ, TNFα and IL2 are reached at day 5 post transplantation." (PMID 23593203, 2013). "Cytokines have been suggested to play a major role in development of systemic and ocular GvHD and increased levels of interleukin (IL)-6 and interferon gamma (IFN-γ) have been observed in serum in patients with systemic acute GvHD." (PMID 22509110, 2012). "In a SCID mouse model of acute GVHD, an increase in interferon-gamma secretion with a synchronized increase in activated Th cells was seen during acute GVHD." (PMID 15285784, 2004). "In murine allogeneic bone marrow transplantation, HGF ameliorated acute graft-versus-host disease (aGVHD) through the reduction of IL12 serum levels and suppression of target organ IFNγ and TNFa mRNA26." (PMID 27917866, 2016).
B cell lymphoma (31 papers, 2009 to 2026). "Loss of HLA in B-cell lymphoma has been shown to be related to a decrease in number of tumor infiltrating lymphocytes and diminished interferon-gamma responses." (PMID 28507804, 2017). "CD14+ primary monocytes were short-term stimulated with IFNγ to accomplish phagocytosis of 3D-cultured B-cell lymphoma cells (spheroids)." (PMID 38020313, 2023). "Unlabeled IFNγ-stimulated monocytes were co-cultured with CFSE-labeled CD20+ B-cell lymphoma spheroids treated with anti-CD20 RTX antibodies of different isotypes: IgG1-4, IgA1-2, or human isotype control antibodies." (PMID 38020313, 2023). "Despite the strong impact on T cell recruitment, we observed a mild effect of CXCL10 and IFNγ blockade in impairing the efficacy of CD20-TCB in a model of B cell lymphoma in humanized mice." (PMID 33406104, 2021). "To understand the regulation of macrophage-mediated ADCC, we used human B cell lymphoma coated with Rituximab as the tumor target and murine macrophages primed with IFNγ as the effectors." (PMID 19148288, 2009). "It is relevant to speculate on the potential role of IFNγ, a Th1 cytokine, in low-grade B-cell lymphoma." (PMID 29293620, 2018). "We first show that IFNγ primed macrophages mediate Rituximab-dependent killing of B cell lymphoma." (PMID 19148288, 2009). "To explore if monocytes mobilize and traffic into the center of spheroids, we labeled IFNγ-stimulated monocytes with PE anti-CD14 and co-cultured them with CFSE-labeled B-cell lymphoma spheroids." (PMID 38020313, 2023). "The T-cell reactivity was specific for Raji because Ramos cells, another human B-cell lymphoma, did not elicit an IFNγ response." (PMID 37087494, 2023). "To determine which FcR participate in the ADP response induced by the most efficient RTX isotypes; RTX-IgG1 and RTX-IgG3, we treated IFNγ-stimulated monocytes with or without blocking antibodies to human FcγRI, FcγRIIa, and FcγRIIIa prior co-culture with RTX-treated B-cell lymphoma spheroids." (PMID 38020313, 2023).
colorectal tumor (31 papers, 2003 to 2025). "PC also inhibited colorectal tumor proliferation, and alleviated colonic inflammation by decreasing the inflammatory cytokines (IFNγ and IL-6) level." (PMID 35447933, 2022). "In KHYG-1 cells treated with the mixture of six LAB from kefir, mRNA expression and IFN-gamma (interferon gamma) secretion levels were increased which enhanced the cytotoxicity to human chronic myelogenous leukemia K562 cells and colorectal tumor HCT116 cells." (PMID 34721321, 2021). "In the current study, the antitumor effect of TCP-1/TNFα and TCP-1/IFNγ alone or in combination was studied in orthotopic colorectal tumor model." (PMID 27342639, 2016). "In this study, we extended to study the effect of TCP-1/TNFα and TCP-1/IFNγ either alone or in combination in orthotopic colorectal tumor model in immune-competent mice." (PMID 27342639, 2016). "TCP-1/TNFα and TCP-1/IFNγ recombinant proteins were prepared and i.v. injected to study the in vivo anticancer effect in orthotopic colorectal tumor model." (PMID 27342639, 2016). "To test whether this mechanism holds true at the tissue-level, we used IFNγ-responsive, patient-derived colorectal tumor organoids and tested if the GBP1:PIM1 interaction inhibitor NSC756093 affected cell viability, organoid growth and stemness." (PMID 37797010, 2023). "Here, we explored the antitumor effect of targeted TNFα or IFNγ in CRC through using fusion protein of TNFα or IFNγ with TCP-1 peptide, a novel ligand which can specifically bind to the vasculature of orthotopic colorectal tumors." (PMID 27342639, 2016). "Furthermore, PHF8 mRNA levels negatively correlated with IFNG, TLR3, IFIH1, STAT1 and OASL expression, suggesting that PHF8 restrains adaptive immune responses in human colorectal tumors." (PMID 37454216, 2023). "In CT26 colorectal tumor-bearing mice, a single round of PDT with porphyrin-lipid photosensitizer incorporated into a polymeric core–shell nanoparticle increased serum TNF-α, IFNγ, and IL-2 the day after PDT." (PMID 36405502, 2021).
injury (31 papers, 2008 to 2025). Damage inflicted on the body as the direct or indirect result of an external force, with or without disruption of structural continuity. "Importantly, human UC-MSCs pretreated with a cocktail containing GC, IFNγ, and TNFα could significantly enhance the therapeutic effect of human UC-MSCs in an acute lung injury mouse model, as reflected by reduced infiltration of immune cells and down-regulation of iNOS in macrophages in the lung." (PMID 38238297, 2024). "Looking at only the population of trauma patients, the concentrations of several proteins, including YKL-40 (CHI3L1), IL-6, IL-8, IFNγ, and others, were positively correlated with patient age." (PMID 38903094, 2024).
mycobacterial infection (31 papers, 2008 to 2025). "The interferon-gamma release assay (IGRA) is another useful diagnostic tool that evaluates the cell-mediated immune response to mycobacterial infections with only 2 mL of heparinized blood." (PMID 40534782, 2025). "Patients with defects in RORC are susceptible to mycobacteriosis and candidiasis due to impaired IFNγ and IL17 immunity." (PMID 38535546, 2024). "The interferon-gamma release assay (IGRA) is used to diagnose cases of feline mycobacteriosis, but the use of serial testing to monitor treatment responses has not been evaluated in this species." (PMID 34073615, 2021). "Interferon gamma (IFNγ) is a cytokine that is produced mostly by T helper 1, cytotoxic T lymphocytes and natural killer cells and plays important roles in controlling mycobacterial infection." (PMID 32883961, 2020). "In cattle, it has been demonstrated that IFNγ is produced during the initial phase of the mycobacterial infection while the reaction induced by SICCT appears later." (PMID 33392284, 2020). "The inability of PD-1−/− mice to control mycobacterial infection is attributed to increased Th1-mediated responses and overproduction of interferon-gamma (IFN-γ)." (PMID 31484550, 2019). "Current options for diagnosing mycobacterial infections in cats are limited to specialist mycobacterial culture, molecular-based methods, i.e., polymerase chain reaction (PCR) and genome sequencing, or the interferon-gamma (IFNγ) release assay (IGRA)." (PMID 34073615, 2021). "Indeed, CD4 T cell responses to Mtb are contained in a CXCR3+CCR6+ Th subset, cells that produce IFNγ, IL-2 and TNFα, and a mutation leading to the loss of the CXCR3+CCR6+ lineage specific transcription factor RORC leads to mycobacteriosis." (PMID 27409590, 2016). "A recent study underlined that bi-allelic RORC loss-of-function mutations resulted in the absence of IL-17-producing T cells and defective IFNγ production by circulating γδ T cells and CD4+CCR6+CXCR3+ αβ T cells, and was associated with mycobacteriosis." (PMID 27409590, 2016).
Parkinson disease (31 papers, 2013 to 2025). A progressive degenerative disorder of the central nervous system characterized by loss of dopamine producing neurons in the substantia nigra and the presence of Lewy bodies in the substantia nigra and locus coeruleus. "We uncovered annotations such as Genetic Association [Parkinson's Disease, GWAS + eQTL] and cellular response to interferon-gamma." (PMID 36333579, 2022). "In the PD group, age-adjusted correlations confirmed IL-4 was associated with UPDRS II (r = 0.321, p = 0.047) and PDQ-39 (r = 0.418, p = 0.009), and interferon gamma (IFN-γ) was associated with Scales for Outcomes in Parkinson’s Disease-Autonomic Questionnaire (SCOPA-AUT; r = −0.564, p = 0.001)." (PMID 40672460, 2025). "Elevated levels of the pro-inflammatory cytokines detected in the brains of Parkinson’s patients have included IFNγ, IL-1β, and TNFα." (PMID 37833807, 2023). "In regard to human Parkinson’s disease, the Th1 cytokines IFNγ and TNF have been shown to be increased in Parkinson’s disease patient blood, while abnormal Treg responses from Parkinson’s disease patients are observed too." (PMID 33704423, 2021). "Since Th1 lymphocytes are the main source of IFNγ and macrophages are the main target cell for this cytokine, these results suggest that the dialogue between Th1 and microglial cells in the substantia nigra of patients with Parkinson’s disease could be a key event in dopaminergic neuronal loss." (PMID 32260305, 2020). "Numerous animal studies have demonstrated a deleterious role of IFNγ in the pathophysiology of Parkinson’s disease." (PMID 32260305, 2020). "Meanwhile, analysis of genes downregulated by both LPS and LPS + IFNγ, clustered in the “turquoise” module, revealed “Huntington’s, Alzheimer’s and Parkinson’s disease” to be among the most significant affected KEGG pathways." (PMID 30382133, 2018). "However, some studies have shown contradictory results regarding the levels of IFNγ and other cytokines in the blood, CSF, or parenchyma in individuals with Parkinson’s disease compared to healthy controls." (PMID 33704423, 2021). "The lesion of substantia nigra in Parkinson’s disease is upregulated and produced higher levels of inflammatory factors, TNF-α, Interleukin-6, and interferon gamma." (PMID 38600296, 2024). "Potentially neurotoxic proinflammatory proteins are expressed in the brains of patients with Parkinson’s disease, including COX and iNOS, TNFα, IL1β and IFNγ." (PMID 32260305, 2020). "However, accumulating evidence shows that Parkinson’s disease is accompanied by immune responses that lead to an increase in serum levels of pro-inflammatory cytokines such as interleukin-6 (IL6), tumor necrosis factor alpha (TNFα), interleukin-1β (IL1B), and interferon gamma (IFNG)." (PMID 32274386, 2020).
peritonitis (30 papers, 2009 to 2025). Inflammation of the peritoneum (tissue that lines the abdominal wall and covers most of the organs in the abdomen). "Initial recruitment of neutrophils and IL-6 secretion during acute peritonitis was described to be dependent on IFNγ." (PMID 31694340, 2019). "The plasma concentration of IFNγ was very low compared to other cytokines, in accordance with what has been observed in experimental models of peritonitis." (PMID 24028733, 2013). "Peritoneal and plasma cytokines (interleukin (IL) 1, tumor necrosis factor α (TNFα), IL-6, IL-10, and interferon γ (IFNγ)) were measured in 66 patients with secondary peritonitis." (PMID 24028733, 2013). "Our results confirm that IL-1, TNFα, IL-6, IL-10 and IFNγ are present at high concentrations in the peritoneal fluid of patients with peritonitis." (PMID 24028733, 2013). "We next determined in vivo impacts of IL-4 and IFNγ on the development of neutrophil-DC hybrids in thioglycollate-induced peritonitis lesions." (PMID 24278484, 2013). "In the course of peritonitis multiple inflammatory mediators are released locally, including IFNγ and TNFα." (PMID 19675677, 2009). "Interestingly, the highest peritoneal IFNγ and TNFα levels are found in peritonitis caused by highly virulent microorganisms, such as S. aureus, precisely the ones that cause more severe demesothelization and that may lead to irreversible peritoneal injury after a single, severe peritonitis episode." (PMID 19675677, 2009).
autoimmune hepatitis (29 papers, 2014 to 2025). Hepatitis caused by autoantibodies. "With autoimmune hepatitis associated with Con A, the serum levels of some inflammatory cytokines (IL-2/4/10, IFNγ and TGF-β) were altered to varying degrees." (PMID 30356792, 2018). "The SDEs also effectively suppressed IFNγ in an ex vivo model of concanavalin-activated mouse Th1 cells, which was a model of autoimmune hepatitis." (PMID 40283895, 2025). "Here, we show suppressive effects of dopamine on IL4 and IFNγ production from hepatic iNKT cells, and demonstrate a protective role of dopamine in inhibiting iNKT cell-mediated autoimmune hepatitis." (PMID 30386344, 2018). "Furthermore, SDEs have been shown to strongly inhibit IFNγ in an ex vivo model of autoimmune hepatitis (AIH)." (PMID 40283895, 2025). "In autoimmune liver disease, MAIT cells are also found to be exhausted with less IFNγ production and upregulation of PD-1 and CTLA-4 is seen in autoimmune liver disease and hepatitis B infection." (PMID 31627733, 2019).
bronchiolitis (29 papers, 2007 to 2026). Inflammation of the bronchioles characterized by swelling of the bronchioles and mucus accumulation. "A high IL4/IFNγ ratio, indicating a type 2 bias, is associated with severe RSV-induced bronchiolitis." (PMID 40636105, 2025). "Here we show that elevated levels of pro-inflammatory cytokines (IL1β, IL6, TNFα, IL18, IL23), regulatory cytokines (IL10, IL17A) and IFNγ were found in the three bronchiolitis cohorts." (PMID 36561744, 2022). "Similar to that seen in calves, infants hospitalized with severe HRSV bronchiolitis, had an increased frequency of IFNγ producing CD8+ T cells, collected by nasal brush, compared to infants with milder upper respiratory tract infections." (PMID 25890239, 2015). "In addition, an association is found between lower levels of systemic IFNγ (a typical marker of type 1 response) and an increased risk of RSV-induced bronchiolitis and the need for ventilation." (PMID 40636105, 2025). "In this sense, it has been proposed that elevated levels of IL6, IFNγ and IL10 among others, protect against hypoxia in bronchiolitis." (PMID 36561744, 2022).